MIR30C2 (microRNA 30c-2)
Synonyms: hsa-mir-30c-2; MIRN30C2; mir-30c-2
Gene: MicroRNA gene on chromosome 6 (71,376,960 to 71,377,031, reverse strand). Ensembl gene ENSG00000199094.
Gene Ontology:
Biological process: miRNA-mediated post-transcriptional gene silencing
Cellular component: RISC complex
Homologues: Orthologues: chimpanzee ptr-mir-30c-2 (100% identical), dog MIR30C2 (99% identical), macaque mml-mir-30c-2 (99% identical), pig ssc-mir-30c-2 (99% identical), rat Mir30c2 (97% identical), mouse Mir30c-2 (96% identical), guinea pig MIR30C2 (85% identical), tropical clawed frog xtr-mir-30c-2 (85% identical), zebrafish dre-mir-30c (69% identical), zebrafish dre-mir-30b (64% identical). Paralogues in human: MIR30C1 (78% identical), MIR30B (61% identical), MIR30D (49% identical), MIR30E (40% identical), MIR30A (35% identical).
Diseases named in the same sentence as MIR30C2 in open-access papers:
MIR30C2 is named in the same sentence as 1 disease in open-access papers, as found by Europe PMC text mining. Sharing a sentence is not in itself a finding about the gene and the disease.
MIR30C2 shares sentences with these, for which no sentence is quoted: breast carcinoma (2 papers).